BCL2 (BCL2 apoptosis regulator)
Diseases named in the same sentence as BCL2 in open-access papers (continued):
Sharing a sentence is not in itself a finding about the gene and the disease.
B-cell lymphoma (continued). "Our case involved high-grade B-cell lymphoma with MYC and BCL2 rearrangement (double hit), treated with dose-adjusted etoposide, prednisone, vincristine, cyclophosphamide, and doxorubicin chemotherapy, resulting in complete resolution." (PMID 41884745, 2026). "Histopathology revealed B-cell non-Hodgkin lymphoma, confirmed by immunohistochemistry (CD20+, BCL2+, BCL6+, MUM1+, and c-MYC+)." (PMID 42221471, 2026). "Conventional cytogenetics analysis identifies patients with translocation of MYC and BCL2 and/or BCL6 as a subgroup of aggressive B-cell lymphoma with poor prognosis and phenotypic proximity to Burkitt lymphoma." (PMID 41364305, 2025). "Diffuse large B-cell lymphoma/high-grade B-cell lymphoma with MYC and BCL2 rearrangements (DLBCL/HGBL-MYC/BCL2) represents a distinct entity of mature aggressive B-cell lymphoma, which is either de novo DLBCL or transformed from indolent lymphoma." (PMID 40230856, 2025). "All these cases were classified as high-grade B-cell lymphoma/DLBCL DH (MYC and BCL2) based on histopathological evaluation." (PMID 40067847, 2025). "Double-hit lymphoma (DHL), a subtype of high-grade B-cell lymphoma characterized by rearrangements of MYC and BCL2 and/or BCL6 genes, represents an aggressive form of large B-cell lymphoma." (PMID 40961031, 2025). "A biopsy of this mass was performed within a few days, and pathology and immunohistochemical examination confirmed the presence of a high-grade B-cell lymphoma, expressing CD5+ and showing triple expression of Bcl2, Bcl6, and c-Myc." (PMID 40941668, 2025). "High‐grade B‐cell lymphoma with MYC and BCL2 and/or BCL6 rearrangements (clinically often referred to as double hit lymphoma [DHIT] or triple hit lymphoma) and HGBL, NOS, were newly introduced in the 4th revised WHO classification." (PMID 39545339, 2025). "High-grade B-cell lymphoma with MYC and BCL2 and/or BCL6 rearrangements constitutes a distinct clinicopathological entity characterized by aggressive behavior, inherent resistance to conventional immunochemotherapy, and suboptimal clinical outcomes." (PMID 41364305, 2025). "About 2% of cases of diffuse large B-cell lymphoma (DLBCL) or high-grade B-cell lymphoma (HGBCL) with MYC and BCL2 rearrangements show expression of terminal deoxynucleotidyl transferase (TdT)." (PMID 41142614, 2025). "The integration of these genomic findings supports the classification as DLBCL/high-grade B-cell lymphoma with MYC and BCL2 rearrangements." (PMID 41374977, 2025). "The pathological subtypes of R/R B-NHL in this cohort were DLBCL, primary mediastinal lymphoma (PML), primary central nervous system lymphoma (PCNSL) and high-grade B-cell lymphoma (HGBL) with MYC and/or BCL2/BCL6 rearrangement." (PMID 40078989, 2025). "Meanwhile, HGBL with two or three rearrangements, due to its high molecular and histological heterogeneity, has been redefined as “diffuse large B-cell lymphoma/high-grade B-cell lymphoma with MYC and BCL2 rearrangements”." (PMID 40243506, 2025). "We recognize several chromosomal rearrangements in the genome of the large B-cell lymphomas, among the most frequent are genes MYC and BCL2 and/or BCL6." (PMID 40126346, 2025). "Key genes such as PAK3, LINC00487, AID, PURPL, and BCL2 were among the most dysregulated, highlighting TIMAP’s role in critical oncogenic pathways in B-cell Lymphoma." (PMID 41170526, 2025). "High-grade B-cell lymphomas with MYC and BCL2 and/or BCL6 rearrangements represent aggressive entities." (PMID 41364305, 2025). "Most patients were diagnosed with DLBCL (37 patients, 97%), whereas one patient had high-grade B-cell lymphoma with MYC and BCL2 rearrangements." (PMID 39907880, 2025). "Diffuse large B-cell lymphoma/high-grade B-cell lymphoma with MYC and BCL2 rearrangements (DLBCL/HGBL-MYC/BCL2) represents a distinct entity of mature aggressive B-cell lymphoma, constituting a substantial gap in the clinical management of DLBCL." (PMID 40230856, 2025).
B-cell lymphoma (continued). "The majority of cases are diffuse large B-cell lymphomas (DLBCLs); however, within this classification, high-grade B-cell lymphomas (HGBLs) are distinguished based on specific genetic alterations (MYC, BCL2, and BCL6 translocations) and histological features." (PMID 40243506, 2025). "PAX5::MYC fusion has been reported in high-grade B-cell lymphoma with MYC and BCL2 rearrangements, DLBCL, and transformed FL." (PMID 41374977, 2025). "In our study, we identified two subtypes of LBCL: diffuse large B-cell lymphoma (DLBCL) (n = 19, 90%) and high-grade B-cell lymphoma (HGBL) (n = 1, 5%) with MYC and BCL2 rearrangements." (PMID 39379648, 2025). "With FISH analysis, we identified three cases of DLBCL/high-grade B-cell lymphoma (HGBCL) with MYC and BCL2 rearrangements." (PMID 40507898, 2025). "DHITsig was originally identified in high-grade B cell lymphoma with MYC and BCL2 rearrangements (HGBCL-DH-BCL2)." (PMID 40674145, 2025). "Definitive biopsy with immunohistochemistry confirmed a high-grade B-cell lymphoma, positive for CD5 and demonstrating triple expression of Bcl2, Bcl6, and c-Myc." (PMID 40941668, 2025). "FISH analysis of a large B-cell lymphoma revealed an atypical BCL6 rearrangement with a 1G1F signal pattern and an IGH::BCL2 fusion." (PMID 41010038, 2025). "This category was maintained by the most recent classifications including exclusively high-grade B-cell lymphoma (HGBL) with MYC and BCL2 rearrangements (MYC/BCL2)." (PMID 41008653, 2025). "In high-grade B-cell lymphoma with MYC and BCL2 and/or BCL6 rearrangements, nivolumab consolidation after DA-EPOCH-R induction was well tolerated and showed 61% CMR." (PMID 40805213, 2025). "EZB subtype was primarily confined to GCB-DLBCL NOS (16%) and specific germinal center-derived DLBCL subtypes, such as T-cell Histiocyte-Rich B-cell Lymphoma and DLBCL/High-Grade B-cell Lymphoma with MYC and BCL2 dual hits." (PMID 40067847, 2025). "GPM confirmed the presence of both IGH::BCL2 and PAX5::MYC, along with 11q aberrations and other complex genomic abnormalities, supporting a diagnosis of DLBCL/high-grade B-cell lymphoma with MYC and BCL2 rearrangements." (PMID 41374977, 2025). "The classic scenario is in mature B-cell lymphomas, such as Burkitt lymphoma, in which the IGH enhancer activates MYC, or follicular lymphoma, in which the IGH enhancer activates BCL2." (PMID 41228256, 2025). "In our patient, FNA indicated abnormal cytology, and subsequent biopsy confirmed a high-grade B-cell lymphoma expressing CD5 and triple expression of Bcl2, Bcl6, and c-Myc." (PMID 40941668, 2025). "All cases were successfully tested for common breakapart molecular events for B-cell lymphomas and PCNLs, BCL6, BCL2, CCND1, IGH, IGL, IGK, and MYC." (PMID 38730692, 2024). "High-grade B-cell lymphomas with MYC and BCL2 and/or BCL6 rearrangements are known for their aggressive clinical course and so are the ones with MYC and BCL2 protein overexpression." (PMID 38397877, 2024). "In addition to histologic classification, further testing for rearrangements of MYC, BCL-2, and BCL-6 is important, as these genetic alterations are associated with poor prognosis, particularly the “double-hit” MYC/BCL-2, currently classified by the WHO-HAEM5 as high-grade B-cell lymphoma." (PMID 39749087, 2024). "DLBCL with rearrangements of MYC, BCL2, and/or BCL6, known as “double-hit lymphoma” (DHL), has been defined as a new entity and renamed “high-grade B-cell lymphoma (HGBCL) with rearrangements of MYC and BCL2 and/or BCL6”." (PMID 38918775, 2024). "One study suggests higher rates of BMB/PET discrepancies among elderly patients and those with high-grade B-cell lymphoma with MYC and BCL2 and/or BCL6 rearrangements." (PMID 38535078, 2024). "FISH demonstrated MYC, BCL2, BCL6, and CCND1 rearrangements and the diagnosis of high-grade B-cell lymphoma with MYC, BCL2, BCL6, and CCND1 was rendered." (PMID 38914869, 2024).
B-cell lymphoma (continued). "Transformation into high-grade B-cell lymphoma with MYC and BCL2 rearrangements, B-lymphoblastic leukemia/lymphoma, classic Hodgkin lymphoma, and plasmablastic lymphoma (PBL) has also been reported." (PMID 38909266, 2024). "A total of 222 specimens from 208 unique patients were identified with a large/high-grade B-cell lymphoma diagnosis and performance of either MYC, BCL2, or BCL6 FISH." (PMID 38903717, 2024). "A retrospective analysis of all diffuse large B-cell lymphomas and high-grade B-cell lymphomas with MYC and BCL2 and/or BCL6 rearrangements diagnosed between 2017 and 2021 at the Institute of Oncology Ljubljana, Slovenia, has been performed." (PMID 38397877, 2024). "Recent updates have removed certain categories, including the previously unclassifiable “B-cell lymphoma” that was identified by “high-grade B-cell lymphoma, with MYC and BCL-2 and/or BCL-6 rearrangements”." (PMID 38535155, 2024). "For example, in B cell lymphoma, the use of BCL6 inhibitors relieved the BCL6-mediated repression of BCL2, leading to addiction to this oncogene." (PMID 39456751, 2024). "Peripheral blood FISH (fluorescence in-situ hybridization) analysis showed evidence of high-grade B-cell lymphoma (HGBCL) with MYC (36.5%) and BCL2 (92.9%) rearrangements." (PMID 39449881, 2024). "B-cell lymphomas with concurrent MYC, BCL2, BCL6, and CCND1 rearrangements appear to be a rare occurrence; however, current standard approaches to DLBCL/HGBL classification do not require routine testing for CCND1 rearrangement." (PMID 38914869, 2024). "In the differential diagnosis, BL needs to be differentiated from other high-grade NHLs, including high-grade B-cell lymphoma, with both MYC and BCL-2, and/or BCL-6 translocations, as well as diffuse large B-cell lymphoma (DLBCL) with MYC translocation." (PMID 39720565, 2024). "Baseline characteristics were well balanced, with slightly more cases of high-grade B-cell lymphoma with MYC and BCL2 or BCL6 rearrangement in the tisa-cel arm (20% vs. 12%)." (PMID 38893108, 2024). "This case describes a complex example of an aggressive TdT‐positive high‐grade B‐cell lymphoma (HGBCL), with MYC and BCL2 rearrangements transformed from follicular lymphoma marked by significant tissue involvement and a concurrent leukemic phase." (PMID 39691256, 2024). "Despite displaying non-specific immunohistochemistry markers such as CD3, CD5, CD10, Bcl-2, CD19, CD20, CD21, and CD23, a definitive diagnosis can only be made after ruling out other small B-cell lymphomas." (PMID 39188441, 2024). "Diffuse B-cell lymphomas with concurrent MYC and BCL2 rearrangements are aggressive neoplasms, although there is some pathologic heterogeneity." (PMID 38978094, 2024). "Fluorescence in situ hybridization (FISH) is an essential ancillary study used to identify clinically aggressive subsets of large B-cell lymphomas that have MYC, BCL2, or BCL6 rearrangements." (PMID 38903717, 2024). "Designating these cases as DHL/THL and qualifying with TdT expression (e.g., “High grade B-cell lymphoma with MYC and BCL2 rearrangements, and expression of TdT”) is preferred by the panel." (PMID 37530792, 2024). "High-grade B-cell lymphoma with MYC and BCL2 rearrangements comprised 9% of all large B-cell lymphoma specimens in our cohort, typical of the 8–10% rate reported in the literature." (PMID 38903717, 2024). "High grade B-cell lymphoma with MYC and BCL2 rearrangements (HGBCL-DH) represents an uncommon B-cell lymphoma (BCL) with aggressive clinical courses and poor prognosis." (PMID 37899423, 2023). "Here, we summarize the different classes of molecules currently under development, which mostly target MYC indirectly in aggressive B-cell lymphomas, paying special attention to subtypes with MYC/BCL2 or BCL6 translocations or overexpression." (PMID 37457123, 2023).
B-cell lymphoma (continued). "Objective responses were seen across DLBCL subtypes, including activated B cell, germinal center B cell and high-grade B cell lymphoma double hit (HGBL-DH, with MYC and BCL2 rearrangements) subtypes." (PMID 37857711, 2023). "DLBCL/high-grade B-cell lymphoma with MYC and BCL2 and/or BCL6 rearrangements carries a particularly poor prognosis." (PMID 36836878, 2023). "Taken together, SC-1 represents a triple-hit B-cell lymphoma cell line, in which IGH rearrangements target FL-specific oncogene BCL2, MYC, as well as a novel target at 17q21, together with fusion of BCL6 and MBNL1." (PMID 37371852, 2023). "Aggressive B‐cell lymphomas with MYC and BCL2 rearrangements form a molecularly distinct group and are listed as definite entities in both classifications." (PMID 36918411, 2023). "WHO-HAEM4R had introduced two categories of HGBL, namely “high-grade B-cell lymphoma with MYC and BCL2 and/or BCL6 rearrangements” and “high-grade B-cell lymphoma, not otherwise specified (NOS)”." (PMID 37190213, 2023). "A number of other LBCLs are infrequently or rarely show EBV infection such as HHV8+ DLBCL, high grade B-cell lymphoma/DLBCL with MYC and BCL2/BCL6 rearrangements and primary mediastinal LBCL." (PMID 36836878, 2023). "Bone marrow tissue biopsy was performed, showing CD20 (+), CD79a (+), CD3 (–), CD5 (-), CyclinD1 (-), Bcl-2 (+), Bcl-6 (-), CD10 (-), MUM-1 (+), and Ki67 (+>50%), and a pathological diagnosis of high-grade B-cell non-Hodgkin lymphoma was made." (PMID 36032118, 2022). "The WHO-HAEM4R entity of high-grade B-cell lymphoma with dual rearrangements of MYC and BCL2 and/or BCL6 has been conceptually reframed and reassigned." (PMID 35732829, 2022). "The translocations of MYC and BCL2 and/or BCL6 in patients with high-grade B-cell lymphomas remained a significant independent predictor of a poorer PFS and OS, but the standard of care for these patients has not been established." (PMID 35153779, 2022). "A biopsy of the hepatic lesion confirmed an infiltration by a high-grade B cell lymphoma with MYC, BCL2 and BCL6 rearrangements." (PMID 36290900, 2022). "Cytogenetic FISH testing for rearrangements of MYC and BCL2 and/or BCL6, helps to identify double-hit or triple-hit, high grade B-cell lymphoma with even poorer outcome and the need for more intensive treatment plans." (PMID 35626243, 2022). "In a subset of B-cell lymphomas, which, based on morphology and phenotype, would be regarded as DLBCLs-NOS, genetic rearrangements of C-MYC, BCL6, and BCL2 have been identified by fluorescent in situ hybridization (FISH) analysis." (PMID 35200580, 2022). "Among 76 patients with high-grade B-cell lymphoma, 44 cases (57.9%) were high-grade B-cell lymphoma, accompanied by MYC and Bcl-2 and/or Bcl-6 rearrangement (HGBLR) patients, and 32 cases (42.1%) were HGBL, NOS patients." (PMID 36618391, 2022). "HGBL includes two types: high-grade B-cell lymphoma, accompanied by MYC and Bcl-2 and/or Bcl-6 rearrangement (HGBLR), and high-grade B-cell lymphoma, not otherwise specified (HGBL, NOS), this type has a low incidence and is clinically rare." (PMID 36618391, 2022). "We found that c-MYC and BCL-2 are key targets of the MSI2/PRMT5 axis, which drives resistance to PRMT5 inhibition in B-cell lymphomas." (PMID 36167829, 2022). "High-grade B-cell lymphoma with translocations involving MYC and BCL2 or BCL6, usually referred to as double hit lymphoma (DHL), is an aggressive hematological malignance with distinct genetic features and poor clinical prognosis." (PMID 35303910, 2022). "Not recognized by either NCI or DFCI are the actual high-grade B-cell lymphoma (HGBCL), B-cell lymphomas with MYC translocation together with either BCL2 and/or BCL6 translocation (double hit/triple hit)." (PMID 36387143, 2022).
B-cell lymphoma (continued). "HGBL is comprised of two types, i.e., HGBL with MYC and Bcl-2 and/or Bcl-6 rearrangements (HGBL-DH or HGBL-TH) and HGBL-NOS, which replaced the category of B-cell lymphoma, unclassifiable, with features intermediate between DLBCL and BL (BCLU)." (PMID 35686130, 2022). "According to the WHO classification, a total of five (17.2%) patients were, therefore, reclassified as aggressive B-cell lymphoma with MYC, BCL2, and/or BCL6 rearrangements (DHL/THL)." (PMID 34830747, 2021). "Synchronous BCL2 and MYC translocations in double-hit high-grade B-cell lymphomas were obvious from cfTNA." (PMID 34204385, 2021). "Double-hit and triple-hit B-cell lymphomas are high-grade B-cell lymphomas defined by the genetic rearrangements of c-MYC and BCL-2 and/or BCL-6, accordingly, by targeted fluorescence in situ hybridization (FISH) studies." (PMID 33692924, 2021). "Chromosomal rearrangements involving BCL2, BCL6 and MYC are commonly found in the most frequent B cell lymphomas, namely follicular lymphomas (FLs) and diffuse large B-cell lymphomas (DLBCLs)." (PMID 33768318, 2021). "Currently, the term High-grade B-cell lymphoma with MYC and BCL2 and/or BCL6 rearrangements is used." (PMID 34945004, 2021). "In 2016, the revised World Health Organization (WHO) guidelines classified this special type to a new category named high‐grade B‐cell lymphoma with rearrangements of MYC, BCL2 and BCL6." (PMID 34698437, 2021). "When MYC translocation occurs simultaneously with BCL2 and/or BCL6, the cases are classified as DH/TH high-grade B-cell lymphoma." (PMID 34207773, 2021). "A practical algorithmic approach for the diagnosis of mature aggressive B-cell lymphoma proposes MYC-R detection first, followed by BCL2 and BCL6 gene analyses in MYC rearranged cases." (PMID 33768318, 2021). "High-grade B-cell lymphoma with concurrent MYC and BCL2 rearrangements (HGBL-DHL) is a rare, aggressive mature B-cell malignancy with a high likelihood of treatment failure following front-line immunochemotherapies." (PMID 33777762, 2021). "Two double-hit high-grade B-cell lymphoma cases were also included, featured by simultaneous MYC and BCL2 translocations that were verified using FISH (Case 18, 19)." (PMID 34204385, 2021). "The dearth of documented consensual clinicopathological characterization of Taiwanese patients with DHL/THL, otherwise designated high-grade B-cell lymphoma (HGBL) with MYC and BCL2 and/or BCL6 rearrangements, informs the present study." (PMID 33807449, 2021). "High-grade B-cell lymphoma, with MYC and BCL2 and/or BCL6 rearrangements (double/triple-hit high grade B-cell lymphoma, HGBL-DH/TH) constitutes a provisional entity among B-cell malignancies with an aggressive behavior and dire prognosis." (PMID 33672644, 2021). "This is the case in double-expressor (DE) DLBCLs and high-grade B cell lymphomas with translocations in MYC and BCL2, also known as “double-hit lymphomas” (HGBL-DH)." (PMID 33670870, 2021). "A total of 170 patients with DLBCL and high-grade B-cell lymphoma with MYC, BCL2, and/or BCL6 rearrangements (DHL/THL), diagnosed and treated in our hospital between 2000 and 2021, were included." (PMID 34830747, 2021). "This study investigated the epidemiological and clinical peculiarities of BCL2 and BCL6 rearrangement in patients with high grade B-cell lymphoma (HGBL) from Taiwan, compared with data from Western countries." (PMID 33807449, 2021). "The recently revised World Health Organization (WHO) classification of tumors of hematopoietic and lymphoid tissues now acknowledges the new and provisional entity of high-grade B-cell lymphoma, with MYC and BCL2 and/or BCL6 rearrangements (HGBL-DH/TH)." (PMID 33672644, 2021). "In B cell lymphoma cells, genomic amplification or pharmacologic induction of NOXA sensitizes cells to BCL2 inhibitors, including ABT-199." (PMID 32764384, 2020).